CRP (C-reactive protein)
Diseases named in the same sentence as CRP in open-access papers (continued):
Sharing a sentence is not in itself a finding about the gene and the disease.
atherosclerosis (continued). "However, genistein reverses Ang II-induced downregulation of PPARγ to inhibit the expression of CRP and matrix metalloproteinase 9 in vascular smooth muscle cells (VSMCs), thereby reducing inflammatory responses in atherosclerosis." (PMID 38699583, 2024). "Our current results suggest that CRP deposition may play a role in the link between atherosclerosis and aneurysms." (PMID 39737187, 2024). "As the level of CRP rises in blood so does the progression of atherosclerosis." (PMID 38961103, 2024). "Furthermore, they bind C-reactive protein (CRP) and subsequently delay macrophage activation and atherosclerosis development." (PMID 39195560, 2024). "Evidence has demonstrated that larger or younger platelets might cause prominent adverse effects such as inflammation response and atherosclerosis by elevating the secretion of inflammatory cytokines (such as IL-6 and CRP) compared to older platelets." (PMID 39195631, 2024). "The hs-CRP level is a reflection of the inflammatory status and, potentially, atherosclerosis." (PMID 39064476, 2024). "Moreover, CRP can trigger activation of the complement system and lead to cardiovascular complications such as atherosclerosis and acute thrombosis mediated by generating excessive C5a." (PMID 39055717, 2024). "CRP serves as a marker for chronic inflammation related to atherosclerosis." (PMID 38816852, 2024). "Serum cardiac biochemical markers (biomarkers) of myocardial damage and atherosclerosis, including high-sensitivity cardiac troponin T and I (hs-cTnT and hs-cTnI), C - reactive protein (CRP), and serum uric acid (SUA), have proven to be helpful for prognostication in STEMI patients." (PMID 37568090, 2023). "C-reactive protein (CRP) plays a critical role in atherosclerosis, and FCGR2A is its main receptor." (PMID 37268894, 2023). "Moreover, CRP is not only a marker of inflammation butalso participates in the progression of atherosclerosis and intravascularthrombosis." (PMID 39076454, 2023). "Compared with young people, the elderly have significantly increased plasma inflammatory markers associated with vascular diseases such as atherosclerosis, including TNF-α, interleukin-1β (IL-1β), interleukin-6 (IL-6), C-reactive protein (CRP), interferon γ (IFN-γ), MCP-1, and MMPs." (PMID 37894840, 2023). "Thus, mutant CRP gave protection against atherosclerosis, demonstrating that a structural change brought on by local inflammation in wild-type CRP is necessary for CRP to limit the growth of atherosclerosis." (PMID 37860004, 2023). "This provides new evidence that CRP promotes the growth of VVin atherosclerosis." (PMID 39077585, 2023). "Symptomatic LEAD included advanced atherosclerosis and tissue inflammation, which might explain the essential role of combined CRP and prolonged QTc interval in predicting death and MACEs." (PMID 37252112, 2023). "In addition, CRP promotes smooth muscle cell proliferation, affects human macrophage polarization enhances thromboxane activity and ultimately leads to atherosclerosis and thrombosis." (PMID 36747210, 2023). "Interestingly, in patients with carotid atherosclerosis, serum miR-183-5p levels were positively correlated with CRP and ox-LDL, which are well-known causes of atherosclerosis." (PMID 37396583, 2023). "However, it is important to note that while measurable circulating biomarkers such as CRP provide valuable information, they are inherently of limited use regarding information about the location and extent of atherosclerosis." (PMID 37765050, 2023). "Age was typically the most highly correlated independent factor on MVA, followed by inflammatory markers (fibrinogen or C-reactive protein) and metabolic (malnutrition-related) parameters (cholesterol or BMI), as was expected for the majority of atherosclerosis markers." (PMID 37893519, 2023). "Previous studies have shown that CRP accelerates the formation and progression of atherosclerosis." (PMID 37025371, 2023).
atherosclerosis (continued). "As an example, in the case of atherosclerosis, CRP was suggested to be not directly causal to the development of atherosclerosis, but rather marks the presence of atheroma or other pro-atherogenic exposures, as well as unmeasured risk factors." (PMID 37479793, 2023). "CRP is capable of stimulating the release of proinflammatory factors and mediating the uptake of low-density lipoprotein into macrophages, which converts them into foam cells and leads to atherosclerosis." (PMID 36894998, 2023). "An increased plasma C-reactive protein (CRP) level is an indicator of premature atherosclerosis." (PMID 37512165, 2023). "This may occur through the regulation of additional biological processes, for example, those relevant to vascular alterations (such as atherosclerosis) that are well captured by CRP levels." (PMID 37264010, 2023). "Additionally, given the inflammatory nature of atherosclerosis, hs-CRP and IL-6 levels are indicative." (PMID 37629496, 2023). "C-reactive protein (CRP) is one of the best-described biomarkers in atherosclerosis." (PMID 37859889, 2023). "Recent clinical trials and experimental researchhave shown that CRP could be a mediator for atherosclerosis as well as abiomarker." (PMID 39077585, 2023). "The involvement of CRP in atherosclerosis is highlighted because it is a fundamental aspect of chronic inflammation, is highly resistant to proteolysis, and is primarily synthesized in the liver in response to proinflammatory cytokines like IL-6, IL-1β, and tumor necrosis factor (TNF)." (PMID 37860004, 2023). "CRP and LDL levels are associated with the development of atherosclerosis." (PMID 36769771, 2023). "Moreover, it was revealed that conformational CRP changes can enable the protein to bind to atherogenic lipoproteins, thus reducing atherosclerosis." (PMID 37873776, 2023). "When patients with ulcerative colitis only and atherosclerosis only were compared, values of CRP (p = 0.000), transferrin saturation (p = 0.000), Ag PLT ADP (p = 0.000), leukocyte (p = 0.001) and fecal calprotectin (p = 0.000) were significantly higher in patients with ulcerative colitis only." (PMID 36984554, 2023). "Therefore, it seems clear that CRP should be used as atherapeutic target for atherosclerosis and CVD." (PMID 39077585, 2023). "CRP has been demonstrated to engage in thrombus formation and significant expression of adhesion molecules in endothelial cells, therefore contributing to the development of atherosclerosis." (PMID 37569355, 2023). "Additionally, given the inflammatory nature of the development of atherosclerosis, high-sensitivity c-reactive protein (hs-CRP) or interleukin-6 (IL-6) are also discussed." (PMID 37629496, 2023). "Based on the OR (95% CI values), CVD is not causally associated with CRP except for atherosclerosis." (PMID 37298077, 2023). "Therefore, we aimed to investigate the association of selected biomarkers relevant for the development of atherosclerosis (CRP, OPG, 25(OH)D, ADMA, and LBP) with cardiovascular events and mortality in patients with T2D during more than 5-year follow-up period." (PMID 37623831, 2023). "IL-6 plays a key role as an upstream cytokine in the propagation of the inflammatory response downstream of atherosclerosis, and the high production of IL-6 stimulates hepatocytes to generate C-reactive protein (CRP), which further amplifies the inflammatory response." (PMID 37485268, 2023). "CRP is not only a non-specific marker of inflammation, but also directly participates in cardiovascular diseases such as inflammation and atherosclerosis, and is the strongest predictor and risk factor for cardiovascular diseases." (PMID 38035283, 2023). "There is, however, international consensus that CRP activates the complement system and binds to Fcγ receptors in atherosclerosis, and thereby may sustain a chronic inflammatory process in the arterial wall." (PMID 35407370, 2022).
atherosclerosis (continued). "Studies indicate that increased serum hs-CRP levels may predict cardiovascular complications such as atherosclerosis." (PMID 36430593, 2022). "Furthermore, CRP is directly involved in the generation of endothelial dysfunction in the process of atherosclerosis." (PMID 36012430, 2022). "This suggests that elevated CRP levels promote systemic inflammation and atherosclerosis." (PMID 35528157, 2022). "CRP is a marker of systemic inflammation and has been proposed to be increased in patients with degenerative AS, similar to the increase found in patients with atherosclerosis." (PMID 35244369, 2022). "Several lines of evidence suggest that CRP may directly contribute to the inflammatory process of atherosclerosis." (PMID 36140236, 2022). "We predicted that the early cardiovascular benefits following bariatric surgery might be attributed to improvements in HOMA-IR, a reduction in CRP to relieve the inflammatory response, and suppression of the formation of atherosclerosis." (PMID 36304549, 2022). "Such antigens came along either as autoantigens like excessive tissue-stranded modified lipoprotein due to misdirected food intake linking CRP with atherosclerosis with an as yet open net effect, or as foreign antigens like SARS-CoV-2 inducing an uncontrolled CRP-mediated autoimmune response." (PMID 35402541, 2022). "Moreover, there were differences in the levels of low-density lipoprotein cholesterol (LDL-C), homocysteine (Hcy), and C-reactive protein (CRP) between the healthy controls and atherosclerosis patients." (PMID 35235755, 2022). "RDW has been previously correlated with CRP and ESR values and has been nominated as an index for estimating autoimmune disease activity and a marker of subclinical inflammation, underlying atherosclerosis and cardiovascular morbi-mortality." (PMID 36293288, 2022). "However, recent studies have noted the possibility that CRP is not only a marker of inflammation but also an accelerator of atherosclerosis." (PMID 35085298, 2022). "Administration of such nanoparticles to the injured aortic wall of a rabbit model of atherosclerosis resulted in an increased level of VEGF and decreased level of C-reactive protein (CRP), followed by a rapid re-endothelisation and inhibition of restenosis, thus, ameliorating atherosclerosis." (PMID 35055117, 2022). "CRP-mediated inflammation in atherosclerosis during SARS-CoV-2 infection may be explained by the presence of monomeric CRP (mCRP) in the lesions." (PMID 36274722, 2022). "Considering both histones and CRP in vascular inflammation and arteriosclerosis, their prolonged presence may suggest accelerated atherosclerosis in the wake of cardiac surgery." (PMID 36068552, 2022). "Concomitant elevation in CRP may provide another synergistic stimulus for the progression of atherosclerosis." (PMID 36068552, 2022). "CRP has been demonstrated to participate in thrombus formation and significant expression of adhesion molecules in ECs, therefore contributing to the development of atherosclerosis." (PMID 36140236, 2022). "Considering the role of inflammation in atherosclerosis, we can speculate that lowering CRP by VD, combined with weight reduction, might have beneficial anti-atherogenic effects." (PMID 35684098, 2022). "CRP-mediated inflammation in atherosclerosis during SARS-CoV-2 infection may be related to the presence of mCRP in the lesions." (PMID 36386929, 2022). "However, future and larger studies are warranted in order to elucidate the role of CRP levels in relation to estrogen, genotype, haplotype and early signs of atherosclerosis to see if these findings are generalizable." (PMID 35428187, 2022). "The results showed that CRP (95% CI = 1.129–15.157, HR = 4.137, P = 0.032), CIMT (95% CI =1.104–11.932, HR = 3.629, P = 0.034), and SOX2-OT (95% CI = 1.200–13.984, HR = 4.096, P = 0.024) were independent risk factors for patients with atherosclerosis." (PMID 35538435, 2022).
atherosclerosis (continued). "CRP has been known as a sensitive marker of chronic systemic inflammation such as atherosclerosis." (PMID 36407305, 2022). "The inflammatory markers of atherosclerosis are HSP 70 and hs-CRP rose, which could be linked to the establishment of atherosclerosis." (PMID 36080424, 2022). "In this context, the value of P-selectin as a CVD biomarker remains to be clarified, independently of other established biomarkers that have demonstrated value for both screening and prognosis of atherosclerosis, i.e., cardiac troponins, natriuretic peptides, or C-reactive protein (CRP)." (PMID 35628490, 2022). "Atherosclerosis represents a state of intense oxidative stress characterized by vascular wall lipid and protein oxidation that contributes to chronic inflammation within the arterial wall, in which CRP is a major player." (PMID 36386929, 2022). "The CRP/Ref‐1 complex might provide an important clue about the inflammatory response and VSMCs during the development of atherosclerosis, suggesting a new viewpoint on multifunctional Ref‐1 processing in cardiovascular disorders." (PMID 35178859, 2022). "Therefore, many studies have included indicators reflecting inflammatory activity, such as CRP and neutrophils, when analyzing atherosclerosis-related adverse events." (PMID 35911526, 2022). "Numerous biomarkers of inflammation play a role in atherosclerosis, but CRP is the major one." (PMID 36381804, 2022). "In addition, a previous study reported superior anti-inflammatory effects of hydrophilic statins compared with lipophilic statins, with higher levels of adiponectin and lower levels of C-reactive protein in atherosclerosis patients." (PMID 34257355, 2021). "Correlation analysis showed a positive association between the number of stenotic atherosclerosis vascular beds with CRP (r = 0.21; p < 0.01) and a negative association with CICs (r = −0.29; p < 0.01)." (PMID 33513851, 2021). "We revealed a positive association between atherosclerosis and CRP, and a negative association between atherosclerosis and CICs." (PMID 33513851, 2021). "As such, it appeared conceivable that increased serum CRP levels could predict complications such as atherosclerosis." (PMID 33921787, 2021). "It is speculated that stimulation of the endothelial intercellular adhesion molecule-1 is mediated by elevated CRP levels and eventually leads to the development of atherosclerosis and, subsequently, cognitive decline." (PMID 34276542, 2021). "Unlike individuals with APOE Ɛ2, individuals with APOE Ɛ4 have lower plasma concentration of APOE and C-reactive protein (CRP), along with higher plasma levels of cholesterol, LDL-C, APOB, lipoprotein (a), atherosclerosis, and BMI, and are at a higher risk of CVD." (PMID 34172062, 2021). "This interaction was further elucidated that the role in accelerating atherosclerosis may involve oxidative stress, cross-reactive epitopes on bacteria and modified low-density lipoprotein and elevated C-reactive protein in patients with periodontitis." (PMID 34532500, 2021). "The prognostic value was independent of interleukin-6, C-reactive protein, and classical risk factors for atherosclerosis." (PMID 33936385, 2021). "Interestingly, the PWV changes were correlated with improvements in C reactive protein serum concentrations, isolating OSA as an independent risk factor for both atherosclerosis and systemic inflammation." (PMID 34575349, 2021). "CRP plays a direct role in the pathogenesis of atherosclerosis and is upregulated significantly in atheromatous plaques, where it may promote low-density lipoprotein cholesterol uptake by macrophages." (PMID 33613636, 2021). "PTX3 can reflect different aspects of atherosclerosis‐related inflammation than that revealed by CRP and may thus provide additional insight into atherosclerosis development and progression." (PMID 33210471, 2021).
atherosclerosis (continued). "Antioxidants and anti-inflammatory properties, mainly in black rice, have been linked to the lowering of inflammation markers, such as high–sensitive C-reactive proteins (CRP) and risks of cardiovascular diseases (specifically, coronary heart disease and atherosclerosis)." (PMID 33810450, 2021). "The effective lipid-lowering drugs used were statin alone and statin in association with fenofibrate, which improved both the lipid profile values and the subclinical atherosclerosis markers (ankle-brachial index, carotid intima-media thickness and high-sensitivity C-reactive protein)." (PMID 33430859, 2021). "CRP has a direct role in promoting the inflammatory component of atherosclerosis." (PMID 34552965, 2021). "A similar multivariate analysis for CRP rendered a non-significant association with previous clinical atherosclerosis." (PMID 34062730, 2021). "LOX-1 binds to multiple ligands besides oxLDL, including C-reactive protein, modified high-density lipoprotein, and remnant lipoprotein, all of which could promote atherosclerosis." (PMID 33659870, 2021). "Both proteins may act synergistically in various inflammatory processes, including atherosclerosis; however, the exact mechanisms of interaction between CRP and OPN are still unknown." (PMID 33668559, 2021). "Increased CRP levels are found in as many as three-quarters of patients with acute stroke; thus, increases in CRP may reflect a systemic inflammatory response following stroke, the extent of tissue injury, or a pre-existing degree of atherosclerosis." (PMID 34135849, 2021). "Additionally, NAFLD patients have elevated inflammatory markers such IL-6, TNF-α, and high sensitivity C-reactive protein (Hs-CRP), as well as the pro-coagulant fibrinogen, which are all key elements in the pathophysiology of atherosclerosis." (PMID 34836382, 2021). "Further investigation is required as to whether the CRP in atherosclerotic plaques specifies its involvement in the progression of atherosclerotic plaques and activates atherosclerosis by stimulating the complement system." (PMID 34754275, 2021). "Likewise, IF has benefits in slowing the development of atherosclerosis since it inhibits the development of atherosclerotic plaques by reducing the concentrations of inflammatory markers, such as IL-6, homocysteine, and C-reactive protein." (PMID 34579056, 2021). "In this concern it is important to note that CRP has been indicated as mediator of atherosclerosis in cardiovascular diseases directly inducing genes that trigger monocyte adhesion along with intracellular recruitment of E-selectin and monocyte chemoattractant protein-1." (PMID 32932765, 2020). "Mounting evidence has established the role of CRP in atherosclerosis." (PMID 32410858, 2020). "Further studies are needed for understanding possible role of CRP in atherosclerosis." (PMID 33033455, 2020). "In the literature, several researches revealed the presence of CRP in atherosclerotic plaques, more specifically in the vascular intima, which suggests a possible role of increased levels of CRP in endothelial dysfunction and atherosclerosis pathogenesis." (PMID 33204538, 2020). "We, therefore, hypothesized that mutant CRP might show an atheroprotective effect in murine models of atherosclerosis." (PMID 32849641, 2020). "CRP can mediate processes involving in the development of atherosclerosis through plaque initiation, formation, and rupture, while it may not be merely a marker of inflammation." (PMID 33424007, 2020). "Finally, the ability of LPC to bind C-reactive protein (CRP) and therefore suppress its pro-atherogenic effect on macrophages and delay the progression of atherosclerosis was reported." (PMID 32599910, 2020).